RNU6-231P (RNA, U6 small nuclear 231, pseudogene)
Gene: Small nuclear RNA gene on chromosome 15 (85,821,855 to 85,821,957, forward strand). Ensembl gene ENSG00000252931.
Homologues: Orthologues: chimpanzee U6 (100% identical), macaque U6 (97% identical), mouse Gm22336 (64% identical), dog U6 (61% identical), mouse Gm55365 (59% identical), pig U6 (54% identical), guinea pig U6 (51% identical), rabbit U6 (50% identical). Paralogues in human: RNU6-477P (71% identical), RNU6-132P (69% identical), RNU6-1200P (68% identical), RNU6-838P (68% identical), RNU6-1013P (67% identical), RNU6-1289P (67% identical), RNU6-188P (67% identical), RNU6-563P (67% identical), RNU6-589P (67% identical), RNU6-1290P (66% identical), RNU6-1303P (66% identical), RNU6-142P (66% identical), and 1283 more.